GPC1 (glypican 1)
Diseases named in the same sentence as GPC1 in open-access papers (continued):
Sharing a sentence is not in itself a finding about the gene and the disease.
tumor (continued). "In addition, immune response against non-GPC1 endogenous tumor antigen was enhanced in syngeneic mouse models, suggesting the role of antigen spread induced by the CAR-T cell therapy in promoting further antitumor activity." (PMID 32228854, 2020). "In the models presented in this study GPC-1 may act as a tumor suppressor in the presence of stromal cells." (PMID 31391540, 2019). "Thus, we collected tumor soluble factors secreted by GPC-1 shRNA and scrambled shRNA PC-3 cells into serum media after 24 hours of incubation." (PMID 31391540, 2019). "Further, GPC-1 inhibition increased PC-3 tumor size in NCr nude mice xenografts." (PMID 31391540, 2019). "For urine sample analysis, 12 out of 14 PCa patient samples (86%) were positive, and 11 out of 14 patients (79%) were positive with confidence in terms of cells with the high level of GPC-1+ expression—the cells which were registered as putative tumour cells in the current study." (PMID 31905736, 2019). "GPC-1+ cells exhibiting the fluorescence signal >1781 arbitrary units, according to the mean (2069)-SD arbitrary units measured from DU-145 cells with ImageJ were registered as putative tumour cells." (PMID 31905736, 2019). "Notably, GPC1+ exosomes level correlated with tumor burden and the survival of PC patients before and after the surgery with utter sensitivity and specificity." (PMID 29928492, 2018). "In this manner, circulating exosomal GPC1 may be seen as a prognostic indicator too, reflecting tumor load and monitoring disease progression and patients' survival." (PMID 30671023, 2018). "Indeed, down-regulation of GPC1 in PDAC cells is associated with reduced proliferation and a reduction in tumor growth, angiogenesis and metastasis in vitro and in vivo." (PMID 29721179, 2018). "Interestingly, when we examined matched tumor and plasma samples, we found that PDACs with high GPC1 protein levels tended to produce crExos with higher GPC1 levels (127.7 ± 66.8 vs. 71.5 ± 24.9 pg/mL), but this was not statistically significant." (PMID 29721179, 2018). "Indeed, high GPC1 expression in PDAC tissues has been associated with perineural invasion (PNI), high grade, large tumor size and poor overall survival (OS) after surgical resection." (PMID 29721179, 2018). "Furthermore, the GPC1+ exosome level reflected the tumor burden and distant metastasis, and a reduction in the number of GPC1+ exosomes was related to increased survival." (PMID 29304816, 2018). "We therefore measured the content of the amount of GPC1+ exosomses in tumour tissues and plasma." (PMID 28233416, 2017). "Overexpression of miR‐96‐5p and miR‐149 significantly decreased GPC1 expression in HT‐29 and HCT‐116 cells, xenograft tumours, plasma in mice bearing HT‐29 and HCT‐116 tumours, and the secretion of GPC1+ exosomes from the HT‐29 and HCT‐116 cells and xenograft tumours." (PMID 28233416, 2017). "Furthermore, tumor tissues were subcutaneously implanted to the SCID mice to assess the anti-tumor effect of anti-GPC1 mAb." (PMID 28445969, 2017). "Importantly, the GPC1 protein levels in GPC1 positive exosomes from the tumour tissues and plasma of CRC patients was significantly higher than that from peritumoural tissues and plasma of healthy subjects, respectively." (PMID 28233416, 2017). "We found that GPC1 was expressed in vascular endothelium cells in ESCC tumor, and tumor angiogenesis might be inhibited by anti-GPC1 mAb in vivo." (PMID 28445969, 2017). "A recent study found that GPC1 is specifically enriched in tumour cell‐derived exosomes." (PMID 28233416, 2017). "Furthermore, GPC1 enhances tumor growth, angiogenesis, and invasion in an oncogenic KRAS-driven mouse model of PDAC." (PMID 29245923, 2017). "Moreover, we identified miR‐96‐5p and miR‐149 as the regulatory factors of GPC1 expression in the tumour tissues and tumour specific exosomes and their roles in the cell proliferation, apoptosis and tumour growth." (PMID 28233416, 2017).
tumor (continued). "Interestingly, GPC1 signal seemed consistently higher in luminal A than in basal-like tumours (for example)." (PMID 28102194, 2017). "Moreover, α3(V) immunoprecipitation from WT/PyMT tumour extracts co-precipitated GPC1 and, conversely, immunoprecipitation of GPC1 co-precipitated α3(V) chains." (PMID 28102194, 2017). "Anti-GPC1 mAb may have a potent anti-tumor effect and represent a novel treatment option for patients with GPC1-positive ESCC." (PMID 28445969, 2017). "Importantly, anti-GPC1 mAb also induced potent tumor growth inhibition in GPC1 positive ESCC patient derived-tumor xenograft models." (PMID 28445969, 2017). "Furthermore, anti-GPC1 mAb showed a significant tumor growth inhibition with decreased angiogenesis compared with IgG treated controls in ESCC xenografted mice." (PMID 28445969, 2017). "Furthermore, it has been reported that host-derived GPC1 in addition to tumoral GPC1 is involved in tumor neovascularization." (PMID 28445969, 2017). "In this ESCC-8 PDX model, expression of GPC1 in the tumor tissue was confirmed by IHC analysis." (PMID 28445969, 2017). "The study showed that both the percentage of GPC1+ exosomes and the GPC1 protein expression in exosomes from tumor tissues and plasma of CRC patients were significantly decreased after surgery compared to those in the peritumoral tissues and plasma of healthy individuals." (PMID 29282096, 2017). "Additional clinical studies must be conducted for the use of serum GPC1 as a tumor marker." (PMID 29245923, 2017). "Earlier reports have described the tumor-promoting role of GPC1 in several cancers." (PMID 29245923, 2017). "Notably, the percentage of GPC1+ plasma exosomes significantly decrease one week after surgery compared to the percentage of GPC1+ plasma exosomes one day before surgery, suggesting that circulating GPC1+ exosomes may be associated with circulating tumor cell count or the total tumor amount in body." (PMID 29254156, 2017). "Moreover, the finding that shRNA knockdown of GPC1 removes ability of FGF2 to rescue KO/PyMT proliferation to WT/PyMT levels, indicates the difference in sensitivity to FGF2 signalling between KO/PyMT and WT/PyMT tumour cells to depend on GPC1." (PMID 28102194, 2017). "Interestingly, both cancer cell–derived and host-derived GPC1 play an important role in tumor development and spread." (PMID 19082421, 2008). "Therefore, COL-V would be a glypican-1-mediated tumour suppressor, although it has already been indicated that the role of this collagen may also be associated with pro-tumour effects, too." (PMID 41463344, 2025). "Moreover, the relation between positive GPC1 IHC staining and tumor grade was highly significant." (PMID 39797955, 2025). "Certain proteoglycans, such as syndecan-1 and glypican-1, promote tumor growth and dissemination by enhancing growth factor signaling and cell migration, whereas others, including decorin and lumican, inhibit tumor progression by modulating immune responses and collagen fibrillogenesis." (PMID 41303704, 2025). "Moreover, GPC-1 functions as coreceptor to potentiate Wnt signaling pathway, which is important for many physiological and pathological processes, including embryonic development, differentiation, cell polarity, and tumor formation." (PMID 39797955, 2025). "Tumor GPC1 may sequester growth factors and promote tumor cell growth." (PMID 37762403, 2023). "GPC1, a glycoprotein, could influence tumor growth and spread." (PMID 37702857, 2023). "Finally, it has been found that high glypican-1 is also a tumor marker of hepatocellular cancer." (PMID 36342580, 2023). "Thus, we explored the correlation between GPC1 expression and tumor immunity based on TCGA data." (PMID 36158119, 2022).
tumor (continued). "For these reasons, functional neutralization of GPC1 by specific mAbs could potentially provide benefits by interfering with tumor growth, metastasis, and angiogenesis, and remodeling the tumor microenvironment to be more responsive to treatment and reduce immunosuppression." (PMID 36142190, 2022). "Similarly, GPC1 expression was upregulated in tumor tissues (p < 0.001)." (PMID 36158119, 2022). "Furthermore, levels of GPC1 correlated with tumor burden and with pre- and post-surgical survival." (PMID 35008381, 2022). "Moreover, exosomal GPC1 level correlates with tumor burden and patient survival." (PMID 32974169, 2020). "However, the purities of GPC2 tumor did not significantly differ from those of GPC1 based on comparable variant allele frequency (VAF) distribution, which suggests that the abundance of normal cells in tumors does not contribute to these proteomic differences." (PMID 32620753, 2020). "Importantly, the murine CAR-T cells enhanced endogenous T cell responses against a non-GPC1 tumor antigen through the mechanism of antigen-spreading and showed synergistic antitumor effects with anti-PD-1 antibody without any adverse effects in syngeneic models." (PMID 32228854, 2020). "Additionally, it has been previously shown that GPC1 may affect FGF-2 signaling in this tumor, contributing to its proliferative aspect and aggressiveness." (PMID 32180897, 2020). "Interestingly, we observed a reduction of GPC-1 mRNA within the primary tumor population." (PMID 31391540, 2019). "Indeed, we have shown that crExos GPC1 measured by ELISA may be useful as a marker of tumor burden and response to surgical resection, but we were unable to distinguish benign pancreatic disease from PDAC pre-operatively." (PMID 29721179, 2018). "High GPC1 crExos may be able to determine PDAC tumor size and disease burden." (PMID 29721179, 2018). "However, crExos GPC1 levels may be clinically useful for determining PDAC tumor size and disease burden." (PMID 29721179, 2018). "Thus, α3(V) chains co-localize with and are bound to GPC1 in WT/PyMT tumours." (PMID 28102194, 2017). "We therefore hypothesized that GPC1 may induce EMT in CRC tumor cells." (PMID 29254156, 2017). "In addition, we found that GPC1 expression was associated with worse biological behaviors of PDAC, such as poorer differentiation and larger tumor diameters, indicating that aberrantly expressed GPC1 may play important roles in tumorigenesis." (PMID 28440066, 2017). "Also, treatment can downregulate GPC1 protein expression in CRC tumour exosomes." (PMID 28233416, 2017). "Thus, our findings that KO/PyMT tumour cells are deficient in proliferative responses to HSPG-dependent (FGF2), but not HSPG-independent (EGF) growth factors are consistent with the possibility that α3(V) chains aid GPC1 co-receptor function." (PMID 28102194, 2017). "The consistent growth features of the tumor cells guarantee that any detected anti-tumor immune response may be more accurately linked to the immune system’s interaction with the GPC1 antigen, rather than alterations in the fundamental development dynamics of the tumor cells." (PMID 40282924, 2025). "Extracellular vesicles (EVs), including exosomes, convey tumor programs that promote PMN formation; EV cargo (e.g., proteins such as glypican-1 or specific microRNAs) are under active investigation as a surrogate of aggressive biology." (PMID 41394398, 2025). "According to the research, exosomes from tumor tissues and plasma of CRC patients had substantially lower percentages of GPC1+ exosomes and GPC1 protein expression after surgery than exosomes from peritumoral tissues and plasma of healthy persons." (PMID 40305328, 2025). "Novel pan-tumor targeting agents, such as TROP-2, Nectin-4, LAT1, GPC-1, and EphA2, are also under development, and clinical translation of radioligand therapy is anticipated." (PMID 40717183, 2025).
tumor (continued). "To investigate the role of CBPRS in the tumour microenvironment (TME) at the single-cell transcriptome level, we analysed the expression patterns of SOD1, MUC2, FKBP4, LOXL2, GPC1 and SNAI3 in different cell types." (PMID 38577594, 2024). "In a study directly comparing the murine and human versions of an anti-GPC-1 CAR T cell, the murine version only demonstrated in vitro tumor cell lysis at 80:1 in contrast to 5:1 for the human construct." (PMID 39335157, 2024). "In-vivo experiments in the BXPC3 xenograft model showed that AT101 was able to bind GPC1 on the cell surface and accumulate in the BXPC3 tumor masses." (PMID 38017492, 2023). "While GPC1 and GPC2 exhibited a strong net upregulation in tumor samples over normal across the board of cancer types, other members like GPC4, GPC5, and GPC6 were characterized by tissue-specific cancer expression patterns." (PMID 36944188, 2023). "Conclusion: [89Zr]GPC1 mAb PET showed high tumoral uptake in the early phase after administration, and targeted α-therapy using [211At]GPC1 mAb showed tumor growth suppression." (PMID 37827841, 2023). "The massive presence of NK cells and macrophages in the tumor sections of mice treated with AT101 is a typical result of this phenomenon, which demonstrated the great potential of this anti-GPC1 mAb in coordinating an immune response." (PMID 38017492, 2023). "Among these proteins, expression levels of Col4A5, GPC1 and HAS2 increased progressively with metastatic potential or tumor size in cell and animal experiments, respectively." (PMID 37903851, 2023). "To elucidate the role of GPC-1 and PI3K/Akt signaling in EAC, we initiated the study by evaluating the mRNA expression levels of GPC-1, PI3K/Akt in EAC tumor tissues through publicly accessible datasets." (PMID 37649964, 2023). "The high expression of GPC1 on the surface of PDAC cells, its involvement in tumor progression and its role in the immunosuppressive tumor microenvironment prompted the development of a novel anti-GPC1 IgM mAb (AT101) for the treatment of PDAC patients." (PMID 38017492, 2023). "More importantly, we showed that combinatorial therapy of GPC-1 knockdown with low-dose Pictilisib (IC25) augmented antitumor efficacy to achieve cell death and tumor regression." (PMID 37649964, 2023). "The ADC demonstrated anti-tumor activity in both the xenograft models and in the PDX, even if the anti-tumor activity is higher in the xenograft murine model, the levels of GPC1 being more homogeneous in comparison with the PDX model." (PMID 36142190, 2022). "Especially, a panel of WNT components, including WNT5A, WNT7B, GPC1, and FZD6 or FZD7, shows tumor tissue-specific increment in CSCC, HNSC, LUSC, and BTCC." (PMID 35850748, 2022). "The results showed that the expressions of GPC1 and GPC2 were higher (P<0.001) in CRC tissues than non-tumor tissues." (PMID 35671267, 2022). "Recent studies have highlighted promising exosome-derived biomarkers for use in future combined strategies, including the cell surface proteoglycan, GPC1, which has been shown to be specifically enriched on PDAC tumour-derived exosomes." (PMID 33451936, 2021). "A panel of tumor-derived extracellular vesicle markers, including EGFR, EPCAM, HER2, MUC, GPC1, WNT2, and GRP94, was investigated." (PMID 33803470, 2021). "The results of GEPIA analysis showed that expression of GPC1, GPC3, GPC4, and GPC6 was significantly higher in PDAC tumor tissues than in normal tissues (P < 0.05)." (PMID 33302876, 2020). "Expression of GPC-1 in PCa is well established and correlates with Gleason score, in line with the known role of GPC-1 in tumour growth, invasion and metastasis." (PMID 32382920, 2020). "Our study confirms that the fluorescent conjugate Miltuximab®-IR800 can target GPC-1 to identify and visualize GBM tumors in vivo, with long retention of fluorescent signal in the tumor." (PMID 32316186, 2020).
tumor (continued). "The high expression rate of gpC1 in BCA suggests this blood group precursor antigen may be a BCA biomarker, and the strikingly high percentage of gpC1 positive CTCs in the advanced stage of triple-negative BCA indicate gpC1 is potentially associated with aggressive tumor behaviour." (PMID 32879924, 2020). "The tumor promoters BASP1, GPC1, PSAT1 and SH3BGRL are reported to be typically expressed in macrophages by the Expression Atlas." (PMID 32466393, 2020). "The GPC1-activated PPP and one-carbon pathway also generate NADPH, which is a reducing equivalent for tumor cells affected by the Warburg effect." (PMID 32620753, 2020). "Glypican 1, an important protein at the center of the GP1 pathway, has significant roles in tumor growth, angiogenesis, and metastasis." (PMID 31594284, 2019). "Inhibition of GPC-1 was reported to impair cellular responses to growth factors such as FGF2, EGF and HGF in PANC-1 (pancreatic carcinoma) cells and decrease tumor formation in nude mice." (PMID 31391540, 2019). "Potential clinical utility of the chip was demonstrated using anti-Glypican-1 (GPC-1) antibody as a model of the primary antibody in immunofluorescent assay for identification and detection of the collected tumour cells." (PMID 31905736, 2019). "We assessed the role of GPC-1 in cell growth and tumorigenesis by inhibiting GPC-1 expression and showed a differential response between in vitro and in vivo tumor models." (PMID 31391540, 2019). "Consistent with this possibility, α3(V)-free ECM from KO/PyMT tumour cells and ECM of WT/PyMT tumour cells in which GPC1 had been knocked down both contained less FGF2 than did control WT/PyMT tumour cell ECM." (PMID 28102194, 2017). "We divided the patients with PDAC into three groups, with high, moderate and low GPC1 expression levels, using two tertiles of RPM values of GPC1 in tumor tissues." (PMID 28440066, 2017). "In this study, we provided initial evidence that significantly elevated GPC1+ exosomes are present in the plasma of CRC patients and can be secreted from CRC tumour cells." (PMID 28233416, 2017). "Therefore, anti-GPC1 mAb may have anti-tumor efficacy in these GPC1-positive cancers." (PMID 28445969, 2017). "miR‐96‐5p and miR‐149 expression in tumour tissues and plasma of CRC patients as well as in the GPC1+ exosomes from CRC patients were significantly decreased compared to that in the peritumoural tissues and the plasma of healthy controls." (PMID 28233416, 2017). "Compared with isotype control mouse IgG2a, administration of anti-GPC1 mAb significantly inhibited the growth of the TE14 xenografts assessed by tumor volume (60.99% ± 5.11% tumor growth inhibition at day 32) and tumor weight." (PMID 28445969, 2017). "In this pilot study, a statistically significant up-regulation of NOTUM and GPC1 ( p-value < 0.0001) and down-regulation of GPC3 ( p-value < 0.001) mRNA levels were observed in all tumor samples." (PMID 26517809, 2015). "The remaining 8 PGs, for which transcripts were expressed at a frequency of 84% (GPC1), 86% (GPC3), 88% (GPC4), 70% (GPC6), 100% (SDC1), 94% (SDC2), 93% (SDC3) and 95% (SDC4) of the tumour cases, respectively, were found to be differently modulated." (PMID 25935541, 2015). "To assess Notum, Glypican-1 and Glypican-3 protein localization in human CRC samples, we performed immunohistochemical analysis on 10 tumor cases and 10 normal matched mucosa specimens." (PMID 26517809, 2015). "Meanwhile, GPC1 positive staining was not related to the presence or absence of tumor necrosis (p = 0.649)." (PMID 39797955, 2025). "Furthermore, PET imaging and therapeutic agents targeting pan-tumor molecules such as LAT1, GPC-1, and EphA2 have already been developed and are currently undergoing optimization for clinical translation." (PMID 40717183, 2025).